MIR1298 (microRNA 1298)
Synonyms: hsa-mir-1298; MIRN1298
Gene: MicroRNA gene on chromosome X (114,715,233 to 114,715,344, forward strand). Ensembl gene ENSG00000221710.
Homologues: Orthologues: chimpanzee ptr-mir-1298 (100% identical).